MMRN1 (multimerin 1)
Description:
Carrier protein for platelet (but not plasma) factor V/Va. Plays a role in the storage and stabilization of factor V in platelets. Upon release following platelet activation, may limit platelet and plasma factor Va-dependent thrombin generation. Ligand for integrin alpha-IIb/beta-3 and integrin alpha-V/beta-3 on activated platelets, and may function as an extracellular matrix or adhesive protein.
Synonyms: ECM; EMILIN4; GPIA*; MMRN
Tractability: Antibody: UniProt places it where antibodies can reach, with high confidence; its Gene Ontology location is reachable by antibodies, with high confidence; UniProt predicts a signal peptide or a membrane-spanning region.
Gene: Protein-coding gene on chromosome 4 (89,879,532 to 89,954,629, forward strand). Ensembl gene ENSG00000138722.
Subcellular location: Secreted
Subcellular location (Human Protein Atlas): Endoplasmic reticulum; Predicted to be secreted
Pathways (Reactome):
Hemostasis: Platelet degranulation
Metabolism of proteins: O-linked glycosylation
Gene Ontology:
Molecular function: protein binding; extracellular matrix structural constituent; calcium ion binding
Biological process: cell adhesion mediated by integrin; negative regulation of wound healing; positive regulation of platelet aggregation; blood coagulation; cell adhesion; negative regulation of cell migration involved in sprouting angiogenesis; negative regulation of vascular endothelial growth factor receptor signaling pathway
Cellular component: extracellular matrix; extracellular region; multimerin complex; platelet alpha granule; endoplasmic reticulum lumen; non-collagenous component of interstitial matrix; platelet alpha granule lumen
Genetic constraint (gnomAD): Loss-of-function variants: 81 observed, 95.91 expected, observed/expected ratio (o/e) 0.84, 90% interval 0.7 to 1.02. The upper end of that interval is the gene's LOEUF score, 1.02, which puts it in group 4 of 6, group 1 being the genes least tolerant of losing a copy. Missense variants: 1,548 observed, 1,452.8 expected, observed/expected ratio (o/e) 1.07, 90% interval 1.02 to 1.11. Synonymous variants: 550 observed, 511.48 expected, observed/expected ratio (o/e) 1.08, 90% interval 1 to 1.15.
Homologues: Orthologues: chimpanzee MMRN1 (98% identical), macaque MMRN1 (94% identical), dog MMRN1 (81% identical), rabbit MMRN1 (78% identical), pig MMRN1 (77% identical), guinea pig MMRN1 (74% identical), rat Mmrn1 (66% identical), mouse Mmrn1 (66% identical), tropical clawed frog mmrn1 (40% identical). Paralogues in human: MMRN2 (15% identical), EMILIN2 (12% identical), EMILIN1 (12% identical), EMILIN3 (7% identical).
Diseases named in the same sentence as MMRN1 in open-access papers:
MMRN1 is named in the same sentence as 87 diseases in open-access papers, as found by Europe PMC text mining. Sharing a sentence is not in itself a finding about the gene and the disease. The quoted sentences say what the papers report.
ovarian carcinoma (8 papers, 2016 to 2025). A malignant neoplasm originating from the surface ovarian epithelium. "Altered expression of MMRN1 has been reported in hepatocellular carcinoma, cervical cancer and ovarian cancer." (PMID 33949771, 2021). "MMRN1 expression is also tied to the progression of ovarian cancer." (PMID 41296429, 2025). "MMRN1 was upregulated in ovarian cancer and was an unfavorable factor in AML." (PMID 37477536, 2023). "MMRN1 is implicated in several types of cancers, including non-small cell lung cancer, thyroid carcinoma, ovarian cancer, and cervical cancer." (PMID 36081907, 2022). "This opposing trend does not exclude MMRN1’s feasibility as biomarker; MMRN1 protein is specifically detected in ovarian cancer." (PMID 35132992, 2022).
gastric cancer (5 papers, 2020 to 2025). A primary or metastatic malignant neoplasm involving the stomach. "MMRN1 downregulation is associated with chemoresistance in rectal cancer and radiosensitivity and associated clinical outcome in gastric cancer." (PMID 35132992, 2022). "MMRN1 also played an important risk factor in gastric cancer microenvironment." (PMID 33949771, 2021). "SP1 regulates MMRN1 expression in vitro in a gastric cancer model." (PMID 35132992, 2022). "This aligns with the observation that in gastric cancer, where SP1 levels are high, MMRN1 levels are downregulated." (PMID 35132992, 2022). "It is worth noting that Multimerin 1 (MMRN1), an E3-related gene closely related to poor prognosis, has not been fully studied in gastric cancer and has important research potential." (PMID 41296429, 2025).
melanoma (5 papers, 2017 to 2023). A malignant, usually aggressive tumor composed of atypical, neoplastic melanocytes. "When analyzing the interaction between melanoma and human umbilical vein endothelial cells (HUVECs), MMRN1 was one of the 30 upregulated genes with a possible role in cell–cell communication and tumour progression." (PMID 35132992, 2022). "This may suggest a possible mechanism of MMRN1-mediated cell adhesion and melanoma-HUVECs communication." (PMID 35132992, 2022).
acute myeloid leukemia (4 papers, 2021 to 2023). Acute myeloid leukemia (AML) is a group of neoplasms arising from precursor cells committed to the myeloid cell-line differentiation. "Multimerin-1 (MMRN1) has been recognized as a novel biomarker that may refine acute myelogenous leukemia risk stratification." (PMID 34903206, 2021). "MMRN1 expression is positively correlated with higher expression of the lncRNA KIAA0125, which, like MMRN1, is included in the prognostic LSC17 for acute myeloid leukaemia and is linked to a poorer prognosis, shorter overall survival and disease-free survival." (PMID 35132992, 2022). "As a platelet protein, multimerin 1 has shown good predictive value as a biomarker for acute myeloid leukemia." (PMID 36081907, 2022).
cervical cancer (4 papers, 2021 to 2022). A primary or metastatic malignant neoplasm involving the cervix. "A1AT, PYCR2, TTR, ApoAI, VDBP, and MMRN1 were expressed considerably differently in serum samples from healthy controls and cervical cancer patients." (PMID 35645371, 2022). "For example, MMRN1 has notable mRNA levels in the cervix and cervical mucus, which is a known component of first-void urine samples which may explain MMRN1 detection in urine, but this will need to be verified to support the use MMRN1 as a biomarker in cervical cancer." (PMID 35132992, 2022).
atherosclerosis (3 papers, 2022 to 2025). A disease characterized by the build-up of fatty material and calcium deposition in the arterial wall resulting in partial or complete occlusion of the arterial lumen. "The main cluster populated by the Oasl1−/−Apoe−/− mouse group (EC Sub-cluster 4) showed increased expression of genes associated with pulmonary hypertension and atherosclerosis, including Selp, Edn1, Ctla2a, Ccl2, Mmrn1, Plvap, and Lgmn." (PMID 36333342, 2022).
bleeding disorder (3 papers, 2015 to 2021). "Many mucocutaneous bleeding disorders remain uncharacterized and MMRN1 defects might go undetected by current bleeding disorder investigations." (PMID 33179420, 2021).
breast carcinoma (3 papers, 2020 to 2022). "Hormones like oestrogen and progestogens contribute to breast cancer risk and oestrogen can affect gene expression patterns, including MMRN1." (PMID 35132992, 2022). "In addition, we identified five ceRNA pairs (i.e., CDH5 with FAM212B, CDH5 with GYG2 in Module 45, TRIB1 with IL33, TRIB1 with INMT, and TRIB1 with MMRN1 in Module 110) that can be used as prognostic markers of breast cancer in BRCA-associated modules." (PMID 32256525, 2020). "Considering the role of hormones in types of breast cancer, it would be interesting to investigate if MMRN1 is hormonally regulated in the future." (PMID 35132992, 2022). "MMRN1 expression patterns have also been correlated with the stage of breast cancer, supporting its potential use in cancer diagnosis." (PMID 35132992, 2022). "Whereas MMRN1 levels appear high in these healthy conditions, MMRN1 levels are downregulated in the majority of reported breast cancer datasets." (PMID 35132992, 2022).
leukemia (3 papers, 2021 to 2026). A malignant (clonal) hematologic disorder, involving hematopoietic stem cells and characterized by the presence of primitive or atypical myeloid or lymphoid cells in the bone marrow and the blood. "MMRN1 expression distinguishes leukaemia stem cells, which contribute to therapy resistance and disease relapse, from leukaemia progenitor cells." (PMID 35132992, 2022). "Many leukemia stem cell like genes of the LSC17 signature diminished after day 14 such as LAPTM4B, MMRN1, ADGRG1 or AKR1C3, but some were upregulated again by day 30, day 70 CD19- and/or day 70 CD19+." (PMID 41145673, 2026). "HOPX, DOCK1, DNMT3B, MMRN1, and ARHGAP22 genes were reported as important leukemia stem cell markers." (PMID 33225420, 2021).
liver fibrosis (3 papers, 2023 to 2025). "The established markers of LyECs (Prox1, Pdpn, Ccl21a, Mmrn1, Reln, and Rassf9) are highly expressed in hepatic LyECs from CCl4-induced liver fibrosis, NASH and BDL mice." (PMID 36632228, 2023).
platelet disorder (3 papers, 2021 to 2022). "MMRN1 platelet-related functions include platelet adhesion, factor V regulation, and MMRN1 deficiency associated with bleeding risks in Quebec platelet disorder." (PMID 36105100, 2022). "MMRN1 platelet-related functions include platelet adhesion, factor V regulation, and MMRN1 deficiency is associated with bleeding risks in Quebec platelet disorder." (PMID 35132992, 2022). "Nonetheless, platelet MMRN1 deficiency might account for some platelet function abnormalities noted in gray platelet syndrome, Quebec platelet disorder, and αδ‐storage pool deficiency." (PMID 33179420, 2021).
renal cell carcinoma (3 papers, 2021 to 2025). "The present study aimed to explore the role of MMRN1 in renal cell carcinoma (RCC) and its related molecular mechanisms." (PMID 40583724, 2025). "MMRN1 facilitates the proliferation and invasion of renal cell carcinoma by activating MMPs via the AMPK pathway." (PMID 41296429, 2025).
bladder cancer (2 papers, 2022 to 2025). "It has been postulated that proteins are secreted or shed from cancer tissues and it has been shown that MMRN1 is being released via exosomes by duodenal cancer cells (for MMRN1 expression in duodenum adenocarcinoma cell line HuTu80), bladder cancer cells, and medulloblastoma cells." (PMID 35132992, 2022).
colorectal cancer (2 papers, 2022 to 2025). A primary or metastatic malignant neoplasm that affects the colon or rectum. "In colorectal cancer, MMRN1 is targeted by has-miR-99b-5p, which is infrequently expressed in overall colorectal tumours, and its upregulation is associated with an increased likelihood of dying." (PMID 35132992, 2022).
dementia (2 papers, 2023 to 2024). Loss of intellectual abilities interfering with an individual's social and occupational functions. "We found that risk allele rs429358 tagging APOEe4 increases the odds of developing dementia, and that rs7668531 near the MMRN1 and SNCA-AS1 genes and an intronic variant rs17442721 tagging LRRK2 G2019S on chromosome 12 are protective against dementia." (PMID 38978726, 2024). "We found that risk alleles rs429358 tagging APOEe4 and rs7668531 near the MMRN1 and SNCA-AS1 genes, increase the odds of developing dementia and that an intronic variant rs17442721 tagging LRRK2 G2019S, on chromosome 12 is protective against dementia." (PMID 37987016, 2023). "We also found a SNP between MMRN1 and the 5’ end of SNCA at the SNCA-AS1 locus but not at the 3’ end to be significantly associated with dementia, consistent with previous candidate gene studies and GWAS." (PMID 37987016, 2023).
Parkinsonism (2 papers, 2015 to 2023). Characteristic neurologic anomaly resulting from degeneration of dopamine-generating cells in the substantia nigra, a region of the midbrain, characterized clinically by shaking, rigidity, slowness of movement and difficulty with walking and gait. "SNCA increased MMRN1 gene expression, associated with late-onset autonomic dysfunction and Parkinsonism after duplication in the Swedish proband." (PMID 36979316, 2023).
Sepsis (2 papers, 2022 to 2023). Sepsis is defined as life-threatening organ dysfunction caused by a dysregulated host response to infection. "sepsis was associated with the C11_Plate cluster, and ESAM, HBG2, MMRN1, PF4V1, SAMD14, SELP, and TGFB1I1 may be important in this context." (PMID 37919720, 2023). "However, few downregulated proteins in sepsis patients compared to HC were AHSG, and PROS1, whereas compared to w/o sepsis, patients were AHSG, PROS1, DEFA1, SERPINA3, MPO, and MMRN1 (Azurophil granule, azurophil granule lumen and secretory granule lumen (GO:0042582, GO:0035578 and GO:0034774))." (PMID 35681439, 2022).
thrombocytopenic purpura (2 papers, 2021 to 2025). Purpura associated with a reduction in circulating blood platelets which can result from a variety of factors. "Moreover, VacA binds to multimerin-1 on platelet surfaces to cause thrombocytopenic purpura." (PMID 40364871, 2025). "Finally, the host immune system comes into action with production of antibodies against H-pylori virulent factor CagA, and binding of VacA with multimerin-1 on platelet surfaces leading to thrombocytopenic purpura." (PMID 34708173, 2021).
anaplastic astrocytoma (1 paper, 2020). "Additionally, there were higher expression levels of EMILIN3 and MMRN1 in anaplastic astrocytoma compared to normal brain tissue." (PMID 32175193, 2020). "In this study, the expression of MMRN1 was positively correlated with tumor grades in LGG; the overexpression of MMRN1 predicted poor prognosis in patients with LGG and indicated anaplastic astrocytoma tissue when compared to normal tissue." (PMID 32175193, 2020).
Aortic dissection (1 paper, 2022). Aortic dissection refers to a tear in the intimal layer of the aorta causing a separation between the intima and the medial layers of the aorta. "Nine proteins (Lumican, FGL1, PI16, MMP9, FBN1, MMP2, VWF, MMRN1, and PF4) related to the pathogenesis of aortic dissection were identified by David /Ease and String techniques as candidate biomarkers for verification test." (PMID 35910577, 2022).
autism (1 paper, 2013). Persistent deficits in social interaction and communication and interaction as well as a markedly restricted repertoire of activity and interest as well as repetitive patterns of behavior. "Genes associated with disease such as MMRN1 (familial parkinsonism), ABAT (autism), and MAP6 (depression and schizophrenia-like symptoms) were also upregulated (for gene functions and references see Suppl." (PMID 23203475, 2013).
chronic lymphocytic leukemia (1 paper, 2021). "MMRN1 is downregulated in chronic lymphocytic leukemia and PTC." (PMID 34335744, 2021).
head and neck cancer (1 paper, 2022). A primary or metastatic malignant neoplasm affecting the head and neck. "That MMRN1 differential expression is cancer-specific has been shown in head and neck cancer, where MMRN1 downregulation is independent of Human Papilloma virus infections, which is often observed in this cancer type." (PMID 35132992, 2022).
Infertility (1 paper, 2024). "A previous study showed that a homozygous variant (c.3454G>A) in the MMRN1 gene was associated with male infertility in a Saudi patient, supporting our novel finding of a potential role for the MMRN1 gene in POI and infertility among women." (PMID 38672141, 2024).
kidney injury (1 paper, 2022). Trauma to the kidney. "Upregulation of MMRN1 has also been observed in injuries including septic shock-associated kidney injury and in serum exosomes from burn patients." (PMID 35132992, 2022).
lung adenocarcinoma (1 paper, 2022). A carcinoma that arises from the lung and is characterized by the presence of malignant glandular epithelial cells. "Network analyses identified the transcription factors SP1 and NFIC as regulators of MMRN1 in lung adenocarcinoma and lung squamous cell carcinoma respectively." (PMID 35132992, 2022).
lung squamous cell carcinoma (1 paper, 2022). "Interestingly, has_circ_0070442 is also one of the top 50 most downregulated circRNAs in lung squamous cell carcinoma, a cancer in which MMRN1 expression is also downregulated (based on data in TNM plot and Oncomine)." (PMID 35132992, 2022). "However, a link between has_circ_0070442 and MMRN1 in lung squamous cell carcinoma has not been reported yet." (PMID 35132992, 2022).
osteosarcoma (1 paper, 2022). A usually aggressive malignant bone-forming mesenchymal neoplasm, predominantly affecting adolescents and young adults. "However, MMRN1 has a possible role in bone remodelling which may be linked to the observation in osteosarcoma." (PMID 35132992, 2022).
papillary thyroid cancer (1 paper, 2022). "In papillary thyroid cancer, MMRN1 is co-expressed with the lncRNA LINC00506 but also targeted by the miRNA has-miR-4709-3p." (PMID 35132992, 2022).
rectal cancer (1 paper, 2022). A primary or metastatic malignant neoplasm that affects the rectum. "Although there is no clear involvement of MMRN1 in these cancers on the basis of the studies, it is interesting that these cancers are less responsive to treatment as are other cancers with differential MMRN1 expression e.g., rectal cancer." (PMID 35132992, 2022). "In rectal cancer, MMRN1 is one of five hub genes that act as prognostic biomarkers and elevated MMRN1 expression is associated with poor prognosis." (PMID 35132992, 2022).
renal carcinoma (1 paper, 2025). A carcinoma arising from the epithelium of the renal parenchyma or the renal pelvis. "The expression of MMRN1 in RCC tissues was detected by qPCR and IHC, and the results showed that the expression of MMRN1 in renal carcinoma tissues was significantly increased compared with that in adjacent tissues." (PMID 40583724, 2025). "To determine whether MMRN1 affects the proliferation and metastasis of renal cancer cells through the AMPK signaling pathway, we performed an AMPK inhibition assay." (PMID 40583724, 2025).
small cell lung carcinoma (1 paper, 2025). Small cell lung cancer (SCLC) is a highly aggressive malignant neoplasm, accounting for 10-15% of lung cancer cases, characterized byrapid growth, and early metastasis. "In small-cell lung cancer, MMRN1 interacts with binding immunoglobulins in the endoplasmic reticulum, maintaining ER stress and promoting cisplatin resistance." (PMID 41296429, 2025).
viral infections (1 paper, 2022). "In addition to cancer, MMRN1 is differentially expressed in other diseases including inflammation and bacterial and viral infections." (PMID 35132992, 2022).